FLVCR1-DT (FLVCR1 divergent transcript)
Synonyms: FLVCR1-AS1; LQK1; NCRNA00292
Gene: Long non-coding RNA gene on chromosome 1 (212,852,105 to 212,858,309, reverse strand). Ensembl gene ENSG00000198468.
Diseases named in the same sentence as FLVCR1-DT in open-access papers:
FLVCR1-DT is named in the same sentence as 2 diseases in open-access papers, as found by Europe PMC text mining. Sharing a sentence is not in itself a finding about the gene and the disease.
FLVCR1-DT shares sentences with these, for which no sentence is quoted: osteosarcoma (1 paper); pancreatic cancer (1).